KLHL32 (kelch like family member 32)
Synonyms: BKLHD5; KIAA1900; UG0030H05; dJ21F7.1
Tractability: Small molecule: it belongs to a druggable protein family. PROTAC: ubiquitination databases record sites on it.
Gene: Protein-coding gene on chromosome 6 (96,924,620 to 97,140,756, forward strand). Ensembl gene ENSG00000186231.
Subcellular location (Human Protein Atlas): Nucleoplasm; Cytosol
Gene Ontology:
Molecular function: protein binding; ubiquitin-like ligase-substrate adaptor activity
Biological process: proteasome-mediated ubiquitin-dependent protein catabolic process
Cellular component: Cul3-RING ubiquitin ligase complex
Genetic constraint (gnomAD): Loss-of-function variants: 27 observed, 50.95 expected, observed/expected ratio (o/e) 0.53, 90% interval 0.39 to 0.73. The upper end of that interval is the gene's LOEUF score, 0.73, which puts it in group 2 of 6, group 1 being the genes least tolerant of losing a copy. Missense variants: 513 observed, 703.79 expected, observed/expected ratio (o/e) 0.73, 90% interval 0.68 to 0.78. Synonymous variants: 224 observed, 260.84 expected, observed/expected ratio (o/e) 0.86, 90% interval 0.77 to 0.96.
Homologues: Orthologues: macaque KLHL32 (99% identical), rabbit KLHL32 (99% identical), chimpanzee KLHL32 (99% identical), dog KLHL32 (99% identical), pig KLHL32 (99% identical), guinea pig KLHL32 (98% identical), rat Klhl32 (98% identical), mouse Klhl32 (98% identical), tropical clawed frog klhl32 (90% identical), zebrafish klhl32 (80% identical). Paralogues in human: KLHL9 (31% identical), KLHL13 (31% identical), KLHL36 (30% identical), KLHL26 (29% identical), KLHL34 (29% identical), KLHL14 (28% identical), KLHL22 (28% identical), KLHL1 (27% identical), KLHL15 (27% identical), KLHL20 (27% identical), KLHL4 (27% identical), KLHL31 (27% identical), and 42 more.
Diseases named in the same sentence as KLHL32 in open-access papers:
KLHL32 is named in the same sentence as 8 diseases in open-access papers, as found by Europe PMC text mining. Sharing a sentence is not in itself a finding about the gene and the disease. The quoted sentences say what the papers report.
Obesity (2 papers, 2017 to 2022). Accumulation of substantial excess body fat. "A GWAS study indicated that KLHL32 may be associated with obesity and type 2 diabetes." (PMID 36006549, 2022). "Studies of obesity have shown highly comparable effects of common variants across major ancestry groups, strongly supporting shared common BMI and obesity loci across populations, although ancestry-specific loci have also been shown, such as KLHL32 in Africans and KLF9 in Asians." (PMID 28515345, 2017).
Tourette syndrome (2 papers, 2015 to 2020). A neurologic disorder caused by defective metabolism of the neurotransmitters in the brain. "A deletion on human chromosome 6 that affects GPR63, NOUFA4, and KLHL32 has been associated with Tourette’s syndrome and obsessive–compulsive disorder." (PMID 31840818, 2020). "Genome-wide association studies revealed a risk loci for bipolar disorder downstream of POU3F2, and a region around KLHL32, GPR63 and NDUFA4 associated with Tourette syndrome and obsessive-compulsive disorder, indicating the importance of these enriched regions for establishing cortical functions." (PMID 26076492, 2015).
pancreatic cancer (1 paper, 2022). "In our PECMS model, KLHL32 appears to play a role in pulling the pancreatic cancer ECM in a positive direction for prognosis." (PMID 36006549, 2022). "KLHL32 expression predicted lower oxidative stress level and more immune cells infiltrate in pancreatic cancer." (PMID 36006549, 2022). "Considering the unsatisfactory results of treatments targeting the ECM in pancreatic cancer, the role of KLHL32 in shaping the ECM and its value for drug development warrant more mechanistic and preclinical studies." (PMID 36006549, 2022). "Moreover, patients in the KLHL32-high group had more infiltrating CD8-positive cells, suggesting that KLHL32 plays a positive role in pancreatic cancer immune cell infiltration and the immune response." (PMID 36006549, 2022). "The condition of CD31 expression in the two groups confirmed that the hypoxic microenvironment in the pancreatic cancer matrix did not translate into the kinetic energy of angiogenesis, and the role of KLHL32 in blocking angiogenesis still needs further investigation." (PMID 36006549, 2022). "GLUT-1 expression was significantly lower in the KLHL32-high group than in the KLHL32-low group, deepening the relationship between KLHL32 and glucose transport in the ECM of pancreatic cancer and highlighting the role of GLUT1 in energy utilization in pancreatic cancer." (PMID 36006549, 2022).
cancer (2 papers, 2018 to 2022). A tumor composed of atypical neoplastic, often pleomorphic cells that invade other tissues. "Currently, there are very few studies on the function of KLHL32 in cancers." (PMID 36006549, 2022). "Eight of these had decreased expression in cancer (KLHL3, KLHL4, KLHL13, KLHL14, KLHL29, KLHL30, KLHL32, and KLHL33) while four genes (ENC1, KLHL12, KLHL17, and KLHL35) had patterns of up-regulated gene expression." (PMID 30647843, 2018). "KLHLs with significant hazard ratios or inverse hazard ratios for four cancer types regardless of direction were KLHL14, KLHL22, KLHL29, KLHL32, and KLHL36." (PMID 30647843, 2018).
KLHL32 also shares sentences with these, for which no sentence is quoted: bipolar disorder (1 paper); chronic obstructive pulmonary disease (1); obsessive-compulsive disorder (1); type 2 diabetes (1).